GCG (glucagon)
Diseases named in the same sentence as GCG in open-access papers (continued):
Sharing a sentence is not in itself a finding about the gene and the disease.
diabetes (continued). "The purpose of this study was to assess the effectiveness of a brief training to improve medical students’ knowledge and attitudes about diabetes, hypoglycemia, and glucagon administration." (PMID 31138204, 2019). "In a study of pancreatic perfusion, the administration of insulin suppressed glucagon secretion in dogs with alloxan-induced diabetes and in rats with STZ-induced diabetes." (PMID 31357734, 2019). "This, now recognized, role of glucagon in diabetes control is a major incentive to have a better understanding of alpha cells dysfunctions." (PMID 30849121, 2019). "Our findings reveal that p52 mediates glucagon-triggered hepatic gluconeogenesis and suggests that pharmacological intervention to prevent p52 processing is a potential therapeutic strategy for diabetes." (PMID 31541100, 2019). "In diabetes, paradoxical glucagon hypersecretion occurs despite the presence of hyperglycemia, and glucagon hyposecretion occurs despite the presence of hypoglycemia." (PMID 31357734, 2019). "Individuals with impaired glucose tolerance or diabetes would have had higher glucagon levels and lower GLP-1 levels at study start which would have influenced the weight loss effect on these hormones." (PMID 31042670, 2019). "Despite the importance of glucagon for normal glucose homeostasis and the aberrant secretion in diabetes, there is limited understanding of the mechanisms by which glucose controls glucagon release." (PMID 30953108, 2019). "In diabetes, both inappropriate glucagon secretion, which is attributed to alpha-cells, and impaired insulin secretion, which is attributed to beta-cells, contributed to hyperglycemia." (PMID 30646613, 2019). "Several experimental and clinical studies are aimed at limiting glucagon secretion and/or action to ameliorate the condition of hyperglycaemia in diabetes by decreasing hepatic glucose output." (PMID 31266981, 2019). "The now recognized role of glucagon in diabetes control is a major incentive to have a better understanding of dysfunctional alpha cells." (PMID 30849121, 2019). "In humans, aberrant expression of glucagon can be associated with pathophysiological or disease conditions (e.g., diabetes, non-alcoholic fatty liver, and glucagon-producing tumor)." (PMID 31551932, 2019). "In fact, paradoxical glucagon hypersecretion under hyperglycemic conditions and impaired glucagon secretion under hypoglycemic conditions are commonly observed in diabetes." (PMID 31357734, 2019). "We demonstrate that chronic hyperglycemia results in changes in glucagon secretion similar to those that occur in diabetes." (PMID 30415925, 2019). "Our participants valued the simple and practical information offered on diabetes management and hypoglycemia as well as how to administer glucagon." (PMID 31138204, 2019). "Following the training, participants’ knowledge of diabetes and hypoglycemia increased and participants answered the majority of glucagon questions correctly." (PMID 31138204, 2019). "Various mouse models of diabetes have also revealed that a percentage of existing β cells can adopt the mature identity of glucagon-producing α cells under hyperglycemic conditions." (PMID 31401713, 2019). "Elevated glucagon level in obesity and diabetes promotes hepatic glucose production and hyperglycemia." (PMID 31541100, 2019). "Currently, there are several different diabetes drugs available worldwide, some of which affect glucagon in various ways and exhibit hypoglycemic action." (PMID 31357734, 2019). "GLP‐1 can improve glucose control in patients with diabetes through several mechanisms which include enhanced insulin secretion from beta cells, delayed gastric emptying, and inhibition of glucagon secretion." (PMID 30635924, 2019). "IN glucagon appears to represent a major breakthrough in the treatment of severe hypoglycemia in insulin-treated patients with diabetes, both children and adults." (PMID 31349701, 2019).
diabetes (continued). "Antagonising glucagon signalling in patients with type 1 and type 2 diabetes also improves glycaemic control and reduces daily insulin requirements, suggesting enhanced insulin sensitivity and signalling." (PMID 30626440, 2019). "Individuals with diabetes often show chronically increased glucagon secretion, which contributes to hyperglycaemia." (PMID 30953108, 2019). "In particular, the absence of other supporting measurements of glucose metabolism, such as glycosylated hemoglobin or glucagon, limits the conclusions regarding the effectiveness of MO treatment in animal models of diabetes." (PMID 31810205, 2019). "On the other hand, glucagon agonism has also been suggested as a potential therapeutic strategy for diabetes treatment due to its potential effect on appetite and insulin secretion." (PMID 31284506, 2019). "Although glucagon increases hepatic glucose production and blood glucose levels, paradoxical glucagon hypersecretion is observed in diabetes." (PMID 31357734, 2019). "Diabetes is a chronic disease, and metabolic factors affecting brain metabolisms, such as serum glucose, insulin, and glucagon, are altered according to disease progression." (PMID 31675964, 2019). "The pleiotropic actions of glucagon on energy balance have, over the last years, made it an attractive molecule for the treatment of diabetes and obesity." (PMID 31405212, 2019). "Insulin has been used to treat diabetes for almost 100 years, whereas the primary clinical use of glucagon is limited to the acute treatment of insulin-induced hypoglycemia." (PMID 29558502, 2018). "Insulin is a vital part of diabetes treatment, whereas glucagon is primarily used to treat insulin-induced hypoglycemia." (PMID 29558502, 2018). "In the case of glycine, it becomes a limiting factor for GSH biosynthesis when hepatic glycine oxidation is enhanced in response to high levels of glucagon or diabetes and in response to protein malnutrition." (PMID 29675131, 2018). "In contrast, all seven vaccinated SOCS1-tg mice were protected from diabetes and showed normal pancreas morphology on day 21 p.i. with healthy exocrine tissue and intense insulin and glucagon staining in the islets of Langerhans." (PMID 29151123, 2018). "Accumulating evidence about glucagon has promoted the development of novel drugs regulating glucagon in patients with diabetes, and clinical trials of these agents for diabetes are underway." (PMID 29535833, 2018). "Such patients will develop brittle diabetes as they require exogenous insulin after surgery and in the apancreatic state lose counter-regulatory homeostatic mechanisms (i.e., glucagon)." (PMID 30788460, 2018). "Restoration of physiological glucagon secretion would also be a major advance, but we must first obtain a clearer idea of why this defect develops in diabetes." (PMID 29417183, 2018). "Conversely, the effects of Xen on GIP-mediated insulin and glucagon release were greatest in humans with impaired glucose tolerance but blunted in those with mild type 2 diabetes mellitus." (PMID 29466430, 2018). "For glucagon, we observed a third-order interaction between diabetes, intervention and time with a higher glucagon concentration in the diabetic group." (PMID 29370144, 2018). "The acute abnormalities of ketosis-prone diabetes have been examined using intravenous glucose tolerance tests, oral glucose tolerance tests, and intravenous glucagon stimulation tests [3•, 6, 11]." (PMID 30280274, 2018). "It is well known that under diabetic conditions, alpha cells paradoxically secrete glucagon, which leads to further aggravation of diabetes." (PMID 29487355, 2018). "This was coupled with the presence of soluble dietary fiber, arabinose, and fructose in both the sample and its compounded diet which delaying gastric emptying, inhibiting glucagon secretion, and stimulating insulin secretion in diabetic mellitus animals." (PMID 29387371, 2018).
diabetes (continued). "It is worth noting that glucose homeostasis is tight regulated by the reciprocal control exerted by insulin and glucagon circulating levels, and that hyperglucagonemia is recognized to account for hyperglycemia and diabetes development." (PMID 30532260, 2018). "For glucagon, we observed a difference in postprandial responses induced by diabetes, intervention and time (P = 0.0340)." (PMID 29370144, 2018). "Not all of the patients who exhibited pancreatic endocrine impairment based on the glucagon stimulation test will develop diabetes." (PMID 30571730, 2018). "This abnormal glucagon secretion has led to strategies to control glucagon action to ameliorate the hyperglycemia of diabetes, such as administering glucagon receptor antagonists or neutralizing antibodies against the glucagon receptor." (PMID 30713523, 2018). "First, impaired glucagon secretion in diabetes is often thought to be due to local factors at the level of the alpha cell." (PMID 29593556, 2018). "Islets of db/db mice presenting with uncontrolled diabetes were assessed in terms of morphological structure and insulin, glucagon, and glutaredoxin 5 expression." (PMID 29593651, 2018). "We used 40-day-old BioBreeding (BB) DRLyp/Lyp rats (a model of spontaneous autoimmune type 1 diabetes) and diabetes-resistant DRLyp/+ and DR+/+ littermates (controls) to investigate beta cell function in vivo, and insulin and glucagon secretion in vitro." (PMID 29209740, 2018). "VMH thioredoxin overexpression completely normalized GI neuronal glucose sensing, glycemia recovery, and glucagon secretion in rats with type 1 diabetes mellitus." (PMID 29593556, 2018). "Abnormally elevated glucagon secretion in diabetes can be reproduced by high-glucose treatment of InR1G cells, and the involvement of high glucose-oxidative stress-JNK-insulin signaling pathway axis has been demonstrated." (PMID 28426798, 2017). "Thus, it was thought to be likely that, in this study, the longer duration of diabetes would account for significantly decreased autonomic response to hypoglycemia associated with the progression of neurological damage, as well as a far greater impaired glucagon response in the hypoglycemia group." (PMID 28683068, 2017). "Pancreatic diabetes usually manifests as “brittle diabetes” with poor glucose control due to impaired insulin, glucagon and pancreatic polypeptide." (PMID 29212278, 2017). "The use of an anti-peristaltic agent (e.g. glucagon, butyl-scopolamine), unless contraindicated (e.g. diabetes or phaeochromocytoma), is the most efficient way to limit bowel motion artefact (LE4)." (PMID 27921160, 2017). "In the area of diabetes research, not only insulin but also glucagon is one of the molecules that is difficult to quantify with ELISA3." (PMID 28761041, 2017). "Research studies on adiposity and diabetes in Asian Indians have been done primarily in context of insulin secretion and insulin resistance, whereas plasma glucagon and its relation to adiposity in this ethnic group remain sparsely researched." (PMID 28634585, 2017). "To date, several mechanisms were suggested to be responsible for the dysregulated glucagon secretion in diabetes." (PMID 28426798, 2017). "Dysregulated glucagon secretion is common in patients with Cystic Fibrosis that develop CF related diabetes (CFRD)." (PMID 28273890, 2017). "A key point of discussion focused on the need for basal insulin to allow for the therapeutic benefit of glucagon blockade in the treatment of diabetes." (PMID 28323959, 2017). "The pathophysiological significance of glucagon is increasingly recognized, and glucagon is considered a potential new therapeutic target for diabetes mellitus treatment, since its dysregulated secretion in the diabetic state affects glycemic status." (PMID 28426798, 2017).
diabetes (continued). "This indicates that the deterioration of insulin signaling in pancreatic α-cells in diabetes can play certain roles in the dysregulation of glucagon secretion similar to that in the classical target organs for insulin activity." (PMID 28426798, 2017). "BDNF regulates feeding in obese rodent models of diabetes and modulates glucose metabolism via an anorectic effect as well as by modulating glucagon secretion from pancreatic α-cells." (PMID 28717164, 2017). "In diabetes, glucagon secretion is paradoxically increased, contributing to the exacerbation of the already existing hyperglycemia." (PMID 28426798, 2017). "Diabetes mellitus, commonly referred to as diabetes, is characterized by hyperglycemia due to impaired insulin secretion and aberrant glucagon secretion." (PMID 27608006, 2016). "Plasma IL-6, a pro-inflammatory cytokine, is elevated in physiological and pathophysiological settings where glucagon is also elevated, such as exercise, diabetes and inflammatory stress." (PMID 27973438, 2016). "Now, in eLife, Pedro Herrera from the University of Geneva and co-workers – including Nicolas Damond as first author – report that inhibiting the action of glucagon to treat diabetes only works if a certain number of β-cells are still present." (PMID 27190125, 2016). "The importance of glucagon signaling in diabetes was recently highlighted in studies performed with glucagon receptor knockout (Gcgr-/-) mice and in animals lacking α-cells due to pancreatic aristaless-related homeobox (Arx) deficiency." (PMID 27092792, 2016). "Blood glucose, plasma insulin, C-peptide I, C-peptide II, and glucagon were measured at various times during development of diabetes in Akita mice." (PMID 28702245, 2016). "Recently it has been shown that Na+/glucose co-transporter (SGLT) inhibitors used for the treatment of diabetes increase glucagon levels in man." (PMID 27535321, 2016). "The basal hepatic expression of PGC-1α is relatively low in fed conditions, but its expression is readily upregulated by fasting, glucagon and diabetes, mainly through an altered insulin–glucagon balance." (PMID 27932985, 2016). "Drugs that block the action of glucagon have been found to reduce the symptoms of mild diabetes in mice and are now being tested in humans." (PMID 27092792, 2016). "Hepatic gluconeogenesis during fasting results from gluconeogenic gene activation via the glucagon–cAMP–protein kinase A (PKA) pathway, a process whose dysregulation underlies fasting hyperglycemia in diabetes." (PMID 27874008, 2016). "Collectively, these mechanisms help to maintain normal glucose levels via counter-regulatory effects of insulin and glucagon on hepatic gluconeogenesis and dysfunction of these mechanisms leads to hyperglycemia in diabetes." (PMID 27990298, 2016). "In consequence, antagonists of glucagon signaling are currently being tested in clinical trials for diabetes." (PMID 27092792, 2016). "Blood samples were collected from indwelling vein catheters for measurements of glucose and the diabetes related hormones insulin, glucagon and active glucagon-like peptide-1." (PMID 26859145, 2016). "In patients with diabetes, glucagon concentrations are elevated in the fasting state and fail to decrease appropriately, or even increase, during an oral glucose tolerance test (OGTT) or after ingestion of a mixed meal." (PMID 27973438, 2016). "Hypersecretion of glucagon in diabetes exacerbates hepatic glucose output, thereby fostering hyperglycemia and ketogenesis." (PMID 27092792, 2016). "Glucagon levels are increasingly being included as endpoints in clinical study design and more than 400 current diabetes-related clinical trials have glucagon as an outcome measure." (PMID 26839899, 2016). "Accordingly, the reduction of islet mass in diabetes results in a proportionally larger decrease of glucagon-producing α-cells than of β- and δ-cells, a situation supposed to counteract hyperglycemia." (PMID 27504459, 2016).
diabetes (continued). "Glucose amplification of forward signalling from β-cell ephrinA to α-cell EphA4 receptors was recently proposed to complement paracrine inhibition of glucagon release and explain glucagon hypersecretion when β-cells disappear in diabetes." (PMID 27044660, 2016). "Glucagon secretion is found to be increased, not only in diabetes, but also in several insulin resistant states, including NAFLD." (PMID 27973438, 2016). "The cost of drugs used for diabetes treatment (insulin, glucagon, and others) reached US$ 548 billion in 2013." (PMID 25852997, 2015). "Since GLP-1 and GIP augment glucose-induced insulin release from pancreatic β-cells, suppresses glucagon secretion, and slows gastric emptying, incretins have been proposed as a potential therapeutic target for the treatment of patients with diabetes." (PMID 25582643, 2015). "This would be consistent with 11β-HSD1-/- mice showing increased insulin but decreased glucose levels, and with the emerging importance of glucagon and α-cells in the etiology of diabetes mellitus." (PMID 26305481, 2015). "It has therefore been recognized that inappropriate glucagon secretion is at least in part responsible for the pathophysiology of diabetes mellitus." (PMID 26378455, 2015). "During placebo infusion, glucagon levels were significantly higher in patients with diabetes compared with healthy lean individuals (p = 0.004), with levels being increased by exendin 9-39 compared with placebo (p = 0.004 and p < 0.001, respectively)." (PMID 26385462, 2015). "CTCF is a general TF that has been reported to mediate the effects of insulin on glucagon expression and therefore is a possible new target for diabetes treatment." (PMID 25399255, 2014). "Glibenclamide therapy also prevented the diabetes-induced changes in insulin and glucagon staining, and in the area of individual islets, or whole pancreas, composed of ins+ and glu+ cells." (PMID 25145789, 2014). "Impaired glucagon counter-regulation and the fear of hypoglycemia is a major deterrent to maintaining tight glucose control in type 1 diabetes mellitus." (PMID 24621811, 2014). "Diabetes is characterized by hyperglycaemia due to impaired insulin secretion and aberrant glucagon secretion resulting from changes in pancreatic islet cell function and/or mass." (PMID 25145789, 2014). "Administration of multiple low doses of streptozotocin resulted in severe insulitis, marked destruction of beta-cells, depletion of pancreatic and plasma insulin, elevation of glucagon and severe diabetes." (PMID 24967820, 2014). "Augmented glucagon secretion, together with impaired β-cell function, happens in the very early phase of pre-diabetes." (PMID 25167060, 2014). "The changes in endocrine cell mass were reflected in serum hormone levels; hence, while insulin levels decreased in both models of diabetes, glucagon levels increased only in the STZ model of diabetes." (PMID 25101835, 2014). "Failure to adequately suppress glucagon secretion from α-cells following a meal contributes to the pathogenesis of type 2 diabetes mellitus." (PMID 24621811, 2014). "Serum levels of glucagon reflected these changes in alpha-cell mass: glucagon levels remained constant in NOD mice over time but increased significantly in STZ-induced diabetes." (PMID 25101835, 2014). "Following 4 weeks of diabetes, islet insulin mRNA and protein were dramatically reduced and glucagon mRNA and protein increased." (PMID 25145789, 2014). "In our mouse model, β-cells (identified by lineage tracing) showed lower insulin and increased glucagon content following 4 weeks of diabetes." (PMID 25145789, 2014). "In type 2 diabetes mellitus, increase in the level of glucagon secretion takes place in both the fasting and postprandial state caused due to either impaired pancreatic α-cell sensing, or lack of suitable α-cell response to insulin." (PMID 25521597, 2014).